GSTM3 (glutathione S-transferase mu 3)
Diseases named in the same sentence as GSTM3 in open-access papers (continued):
Sharing a sentence is not in itself a finding about the gene and the disease.
Age-related cataract (4 papers, 2019 to 2024). A type of cataract (opacification of the lens) that forms during the course of aging. "For senile cataracts, GSTM3, which is both identified in plasma and brain proteins and the downregulation of which in the lens epithelial cells (LECs) made LECs more susceptible to oxidative stress, induces the formation of cataracts." (PMID 39408566, 2024).
pancreatic cancer (4 papers, 2019 to 2024). "This study aimed to explore the role of GSTM3 in the malignant behavior and metabolic aspects of PC, its clinical significance, and its possible molecular mechanism in pancreatic cancer." (PMID 32984010, 2020). "Moreover, we also investigated the role of GSTM3 in pancreatic cancer cells using loss- and gain-of-function strategies, despite the fact that GSTM3TV2 does not affect GSTM3 expression." (PMID 31514732, 2019). "Our data revealed that GSTM3 did not significantly affect gemcitabine sensitivity of pancreatic cancer in vitro and in vivo, which implied that the oncogenic role of GSTM3TV2 in pancreatic cancer did not involve crosstalk with GSTM3." (PMID 31514732, 2019).
prostate carcinoma (4 papers, 2017 to 2024). A carcinoma that arises from epithelial cells of the prostate gland. "GSTM1, GSTM3 and ABCC6 were metabolism related genes whose abnormal regulation may contribute to prostate cancer progression." (PMID 29190897, 2017).
Alzheimer disease (3 papers, 2021 to 2023). A progressive, neurodegenerative disease characterized by loss of function and death of nerve cells in several areas of the brain leading to loss of cognitive function such as memory and language. "In a recent study, researchers have identified and chosen three cerebrospinal fluid (CSF) markers, TNFRSF1B, CXCL10, and SPP1, along with three blood markers associated with Alzheimer’s disease (AD), which are GSTM3, TGFB1, and NKTR." (PMID 38259635, 2023). "Among candidate modifier genes involved in neurological development and functioning, at least four genes are closely related to Alzheimer’s disease including FIS1, DDX39B, PRND, GSTM3." (PMID 36553485, 2022).
asthma (3 papers, 2008 to 2019). "Piirilä also studied GSTM3 in relation to diisocyanate-asthma and found later reactions in the bronchial provocation test among GSTM3*AA individuals." (PMID 18447907, 2008). "We have earlier observed in a study population of 182 workers exposed to di-isocyanates, 109 of whom had earlier been diagnosed with asthma, that genetic factors, especially the GSTM3 and NAT2 genotypes, modified risk for occupational asthma and allergic responses to di-isocyanate exposure." (PMID 31649932, 2019).
clear cell renal cell carcinoma (3 papers, 2016 to 2022). "In the case of clear cell renal cell carcinoma, the presence of variant GSTM3*C allele (rs1332108) was associated with lower GSTM3 protein expression in tumor tissue, in comparison with non-tumor tissue, as well as with poorer patients’ prognosis." (PMID 35205816, 2022). "Dysregulation of glutathione‐S‐transferase M3 (GSTM3) has been related to clear cell renal cell carcinoma (ccRCC) in our former study." (PMID 29569387, 2018).
lung disease (3 papers, 2017 to 2025). "The mean DNA methylation at GSTM3 was not significantly different in CF and control samples; however, it was associated with CF lung disease severity in NEC samples (ANOVA p = 0.016)." (PMID 28289476, 2017). "Moreover, the DNA methylation level at three genes (GSTM3 in NEC and HMOX1 and EDNRA in blood samples) was associated with lung disease severity." (PMID 28289476, 2017).
alcoholic liver damage (2 papers, 2022). "Glutathione detoxification enzyme genes, including Gsta1, Gstm3, Gstm1, Gstp1, Gclm, and Gclc, play important roles in protecting against alcoholic liver damage and diseases." (PMID 36359319, 2022). "Glutathione detoxification enzymes including Gsta1, Gstm3, Gstm1, Gstp1, Gclm, and Gclc play important roles in protecting against alcoholic liver damage and diseases." (PMID 35565941, 2022).
atherosclerosis (2 papers, 2019 to 2023). A disease characterized by the build-up of fatty material and calcium deposition in the arterial wall resulting in partial or complete occlusion of the arterial lumen. "The results of RNA sequencing analysis showed that many antioxidant genes were enriched in Fluid shear stress and atherosclerosis pathway, including MGST1, GSTM3, GSTA1, SOD2 and GSTA4." (PMID 36978937, 2023).
cholestasis (2 papers, 2015 to 2017). Impairment of the bile flow caused by obstruction within the liver, or outside the liver in the bile duct system. "After ANIT-induced cholestasis was treated with fenofibrate, the levels of Gsta2, Gsta4, Gstm3, and Gpx2 were significantly decreased (P < 0.01)." (PMID 28855630, 2017). "In our study, the expression levels of Gsta2, Gsta4, Gstm3 and Gpx2 were increased in the ANIT-induced cholestasis." (PMID 28855630, 2017). "Hepatic mRNA levels of GSTM1, GSTM2, and GSTM4 in patients with cholestasis were decreased to 38%, 46%, and 43% of control, respectively (p<0.05 for all), while GSTM3 and GSTM4 mRNA levels were not significantly changed." (PMID 25798860, 2015).
cystic fibrosis (2 papers, 2017 to 2021). Autosomal recessive disorder caused by pathogenic variants in the CFTR gene (cystic fibrosis transmembrane conductance regulator), which encodes a chloride and bicarbonate channel expressed in epithelial cells, and follow the diagnosis criteria. "Also, lower DNA methylation levels at GSTM3 were associated with the GSTM3*B allele, a polymorphic 3-bp deletion that has a protective effect in cystic fibrosis." (PMID 28289476, 2017). "DNA methylation was associated with pulmonary severity in three genes (HMOX1, GSTM3, and EDNRA) and with a polymorphic deletion that has a protective effect in cystic fibrosis at one gene (GSTM3)." (PMID 28289476, 2017).
emphysema (2 papers, 2009 to 2023). "The expressions of all genes were disease associated, except for GSTM3 which was up regulated in the moderate emphysema cases." (PMID 19723343, 2009). "Studies in emphysema have demonstrated that the expression of GSTM3 was upregulated in mild illness, while other studies describe SNPs associated with a lower FEV1/FVC ratio." (PMID 36825998, 2023). "Gene expression profiling of lung from emphysema patients identified seven candidate genes associated with emphysema severity including COL6A3, SERPINF1, ZNHIT6, NEDD4, CDKN2A, NRN1 and GSTM3." (PMID 19723343, 2009). "The candidate genes (CDKN2A, GSTM3, COL6A3, SERPINF1, NRN1, NEDD4 and ZNHIT6) had ontologies that were relevant to emphysema progression, including cell cycle regulation (CDKN2A), collagen (COL6A3), anti-angiogenesis (SERPINF1) and oxidative stress (GSTM3)." (PMID 19723343, 2009).
esophageal squamous cell carcinoma (2 papers, 2021 to 2022). Esophageal squamous cell carcinoma (ESCC) is a type of esophageal carcinoma (EC) that can affect any part of the esophagus, but is usually located in the upper or middle third. "GSTM3 polymorphism was a significant risk factor, and its expression was negatively correlated with disease free survival in esophageal squamous cell carcinoma." (PMID 35965498, 2022). "However, the relationship between GSTM3 expression and the clinical prognosis of esophageal squamous cell carcinoma (ESCC) has not been studied to date." (PMID 33482859, 2021).
glaucoma (2 papers, 2020 to 2024). Increased pressure in the eyeball due to obstruction of the outflow of aqueous humor. "A total of 11 unique protein-coding genes posterior probability (PP) of H4 > 0.70 finally remained, including GSTM3 for senile cataract, WARS1, C3, IGFBP7, and PILRA for AMD, ECI1, LCT, and NPTXR for glaucoma, EFEMP1 for myopia, and SIRPG and SIGLEC14 for DR." (PMID 39408566, 2024).
Hypertension (2 papers, 2021 to 2025). The presence of chronic increased pressure in the systemic arterial system. "GSTM3, a detoxification enzyme, is highly polymorphic and associated with several cardiometabolic phenotypes, including hyperinsulinemia, type 2 diabetes, hypertension, and polycystic ovary syndrome (PCOS)." (PMID 41006818, 2025).
melanoma (2 papers, 2021 to 2024). A malignant, usually aggressive tumor composed of atypical, neoplastic melanocytes. "In melanoma, it was shown that GSTM3 expression correlated with melanoma malignancy." (PMID 34943045, 2021).
meningioma (2 papers, 2010 to 2015). A generally slow growing tumor attached to the dura mater. "When comparing meningiomas with metastases, the two genes that demonstrated the highest mRNA levels, namely AOX1 (M = 12.81) and GSTM3 (M = 7.89) also differed statistically significantly between the two groups (UAOX1 = 5, p = 0.001, r = -0.61 and UGSTM3 = 8, p = 0.002, r = -0.57, respectively)." (PMID 26580399, 2015).
myopia (2 papers, 2024 to 2026). "ATF3, GRIN2B, and GSTM3 have emerged as promising oxidative stress-related biomarkers with significant potential for understanding myopia pathology." (PMID 41912634, 2026).
nasopharyngeal carcinoma (2 papers, 2024 to 2025). A carcinoma arising from the nasopharyngeal epithelium. "Interestingly, GSTM3 was found to confer radiosensitivity to nasopharyngeal carcinoma cells in vitro by inhibiting the expression of GPX4 and influencing the production of PUFAs by indirectly increasing polyunsaturated fatty acid production via fatty acid synthase (FASN) enzyme stability." (PMID 40143107, 2025).
Obesity (2 papers, 2021 to 2024). Accumulation of substantial excess body fat. "Oxidative stress is one of the factors involved in the pathogenesis of obesity, and increased expression of Gsta and Gstm3 has been shown to reduce the levels of oxidative stress associated with obesity." (PMID 38998524, 2024).
varicocele (2 papers, 2015 to 2024). A condition characterized by the dilated tortuous veins of the spermatic cord with a marked left-sided predominance. "The increase in GSTM3 protein expression suggests its increased role in the detoxification in varicocele patients." (PMID 25890347, 2015). "GSTM3 was overexpressed in the unilateral varicocele group and present in a high abundance." (PMID 25890347, 2015).
Arthritis (1 paper, 2020). Inflammation of a joint. "We examined specific glutathione pathway genes including GSTM6, GSTM3, and GPX6, which were differentially expressed in PON1Tg mice compared to WT mice after arthritis induction in our initial pathway analysis." (PMID 33033318, 2020).
astrocytomas (1 paper, 2015). "A correlation between the gene expression and the protein product was observed for AOX1, GSTP1 and GSTM3 in astrocytomas." (PMID 26580399, 2015).
Barrett adenocarcinoma (1 paper, 2021). An adenocarcinoma arising from Barrett metaplastic epithelium in the esophagus. "Epigenetic inactivation of GSTM3 has been reported in Barrett’s adenocarcinoma." (PMID 33482859, 2021).
bipolar disorder (1 paper, 2024). A disorder of the brain that causes unusual shifts in mood, energy, activity levels and the ability to carry out day-to-day tasks. "VWA8 (von Willebrand domain-containing protein 8), SNAP29 (Synaptosomal-associated protein 29), RIF1 (Replication Timing Regulatory Factor 1), AQP4 (Aquaporin-4) and GSTM3 (Glutathione S-Transferase Mu 3) were some relevant differentially expressed genes detected in the bipolar disorder datasets." (PMID 39727940, 2024).
chronic hepatitis B (1 paper, 2019). "Specifically, in patients with acute-on-chronic hepatitis B liver failure (ACLF), GSTM3 gene promoter methylation levels were significantly elevated compared to those in patients with chronic hepatitis B and healthy controls, and levels of GSTM3 methylation were associated with prognosis of ACLF." (PMID 32082163, 2019).
colon adenoma (1 paper, 2016). An adenoma that arises from the colon. "Besides, GSTM3 and also MGST3 (Microsomal Glutathione S-Transferase 3) were induced in human colon adenoma cells by the chemoprotector butyrate, while not in highly transformed neoplastic colorectal cells." (PMID 27206673, 2016).
head and neck cancer (1 paper, 2014). A primary or metastatic malignant neoplasm affecting the head and neck. "Glutathione S-transferase M3 (GSTM3) is an important member of the GSTs that plays a critical role in the development of head and neck cancer (HNC)." (PMID 24416175, 2014).
insulin-resistant (1 paper, 2024). "In diabetic and insulin-resistant mice, the gene expression levels of Gstm3 are reduced." (PMID 39330516, 2024).
laryngeal carcinoma (1 paper, 2014). Carcinoma that arises from the laryngeal epithelium. "This meta-analysis suggests that the GSTM3 A/B polymorphism may be an important protective factor for HNC, especially of laryngeal cancer and Caucasian populations." (PMID 24416175, 2014). "In summary, this meta-analysis indicates that the GSTM3 A/B polymorphism may be an important protective factor for HNC, especially of laryngeal cancer and Caucasian populations." (PMID 24416175, 2014).
liver failure (1 paper, 2016). A liver disease characterized by the liver losing or has lost all of its function. "For example, aberrant methylation of CpG island of the GSTM3 gene promoter is involved in oxidative injury upon liver failure." (PMID 27490558, 2016).
metabolic syndrome (1 paper, 2024). A cluster of metabolic risk factors for CARDIOVASCULAR DISEASES and TYPE 2 DIABETES MELLITUS. "The remaining ten drugged proteins were targeted by compounds indicated for treatment of cancers (CAN2, EPHB1, ERAP1, GSTM3, NQO1, and PVRL4), mitochondrial and muscular disease (NQO1), and metabolic syndrome (CEL)." (PMID 39434187, 2024).
neutropenia (1 paper, 2024). A decrease in the number of neutrophils found in the blood. "We observed the correlation of GSTM3 rs3814309 rare CC genotype with an increased risk of early neutropenia." (PMID 39596349, 2024).
ovarian carcinoma (1 paper, 2021). A malignant neoplasm originating from the surface ovarian epithelium. "Glutathione S-transferase mu 3 is downregulated in ovarian cancer as demonstrated using proteomics analysis." (PMID 33482859, 2021).
seminoma (1 paper, 2022). A radiosensitive malignant germ cell tumor found in the testis (especially undescended), and extragonadal sites (anterior mediastinum and pineal gland). "NRF2 (rs6721961), GSTM3 (rs1332018), SOD2 (rs4880) and GPX3 (rs8177412) polymorphisms were assessed in 88 patients with testicular GCT (52 with seminoma) and 88 age-matched controls." (PMID 35205816, 2022). "However, the herein assessed GSTM3 (rs1332108) polymorphism did not prove to be a significant biomarker of risk for testicular GCT development, nor for its most common pathohistological subtype—seminoma." (PMID 35205816, 2022).
cancer (29 papers, 2003 to 2025). A tumor composed of atypical neoplastic, often pleomorphic cells that invade other tissues. "GSTM3 reportedly predicts high susceptibility, tumour malignant behaviours, and poor prognosis in some cancer types." (PMID 38228715, 2024). "Overall, these studies suggest that GSTM3 not only causes detoxification but also induces glycolysis in cancer." (PMID 34209254, 2021). "GSTM3 is a critical GSTs variant and previous evidences showed that GSTM3 polymorphism is associated with an increased risk to develope a cancer." (PMID 31354629, 2019). "Genetic studies of CC have demonstrated that polymorphisms in the GSTM3 gene are associated with a greater risk of developing this cancer." (PMID 29774096, 2018). "GSTM3 had been found to play a role in detoxification of carcinogens and modulating cancer susceptibility 40]." (PMID 27053949, 2016). "The GSTM3 polymorphism could confer different efficiencies in the metabolism of carcinogens and has been shown to modulate various cancers’ risk." (PMID 36982681, 2023). "Many GSTs, e.g., GSTO1, GSTP1, GSTK1, GSTA4 and GSTM3, are reported to cause resistance in cancer." (PMID 36428646, 2022). "GSTM3-rs1799735 has been associated with various types of cancers with different effects." (PMID 26857559, 2016). "Therefore, there were 14 case-control studies from 10 publications with 2110 cancer cases and 2259 controls concerning GSTM3 A/B polymorphism." (PMID 24416175, 2014). "The GSTM3 polymorphism could, therefore, confer different efficiencies in the metabolism of carcinogens and has been shown to modulate various cancers risk." (PMID 24416175, 2014). "Consequently, there is a possibility that smokers carrying the GSTM1 or GSTP1 or GSTM3 risk genotype will be susceptible to cancer if the DNA adducts remain unrepaired." (PMID 24416175, 2014). "The contradictory results might attribute to that the functions of GSTMs, especially in GSTM3/4, was induce detoxification of electrophilic compounds, such as cancer-causing toxins, anticarcinogens and products of oxidative stress via conjugating with glutathione." (PMID 35965498, 2022). "Recent research on GSTM3 in cancers and other diseases indicates that it has significant effects on individual susceptibility, disease progression, and response to therapy (including chemotherapy) 56-58." (PMID 40740240, 2025). "In comparison to normal tissues, Nos2, Hgf, Lama1, Csf3r, Csf2rb2, Col4a1, Col4a2, Adcy2, Adcy4, Gstm3 and Gstm6 were identified as the most significant genes in cancer pathways." (PMID 37774039, 2023). "Further studies are required to unveil the anti-cancer drug resistance and radiation insensitivity of GSTM3 in ESCC." (PMID 33482859, 2021). "Glutathione S-transferase mu 3 (GSTM3) plays a crucial role in tumor progression in various cancers." (PMID 33482859, 2021). "Our report also points to the need for further studies about the role of anti-cancer drug resistance and radiation insensitivity of GSTM3 in ESCC." (PMID 33482859, 2021). "Elevated glycolysis implied cancer progression in the GSTM3 silenced group, in keeping with the anti-tumor effect of GSTM3." (PMID 32984010, 2020). "Particularly, GSTM3 has been shown to be dysregulated in various cancers such as renal cancer, prostate carcinoma, breast carcinoma, hepatic carcinoma, colorectal carcinoma, and cervical malignancy." (PMID 32984010, 2020). "Recently, GSTM3 has been identified to exert an oncogenic or anti-tumor role in different cancers by targeting various signaling pathways." (PMID 32984010, 2020). "GSTM3 is a GST-Mu class member, which is known to be involved in regulating the susceptibility to cancer." (PMID 25202346, 2014). "In the context of cancer treatment, the role of GSTM3 is gaining attention." (PMID 40740240, 2025). "Whether other upstream regulators of GSTM3 such as the lncRNA GAS5 could also play a role in resistant cancer cells needs to be examined further." (PMID 36428646, 2022).